PRKAR1A (protein kinase cAMP-dependent type I regulatory subunit alpha)
Description:
Regulatory subunit of the cAMP-dependent protein kinases involved in cAMP signaling in cells.
Synonyms: TSE1; PKR1; PRKAR1; CNC1; ACRDYS1; ADOHR; CAR; CNC; PPNAD1; Prkar1alpha
Tractability: Small molecule: a structure with a bound ligand is known. Antibody: UniProt places it where antibodies can reach, with high confidence; its Gene Ontology location is reachable by antibodies, with medium confidence. PROTAC: ubiquitination databases record sites on it; its protein half-life has been measured.
Target class: Kinase; Protein kinase regulatory subunit; Enzyme
Gene: Protein-coding gene on chromosome 17 (68,511,780 to 68,551,319, forward strand). Ensembl gene ENSG00000108946.
Subcellular location: Cell membrane
Subcellular location (Human Protein Atlas): Cytosol
Pathways (Reactome):
Disease: ADORA2B mediated anti-inflammatory cytokines production; ALK mutants bind TKIs; FCGR3A-mediated IL10 synthesis; Signaling by ALK fusions and activated point mutants
Signal Transduction: DARPP-32 events; GPER1 signaling; Hedgehog 'off' state; PKA activation
Metabolism: Glucagon-like Peptide-1 (GLP1) regulates insulin secretion; PKA activation in glucagon signalling
Cellular responses to stimuli: High laminar flow shear stress activates signaling by PIEZO1 and PECAM1:CDH5:KDR in endothelial cells
Hemostasis: Factors involved in megakaryocyte development and platelet production
Neuronal System: CREB1 phosphorylation through the activation of Adenylate Cyclase
Transport of small molecules: Vasopressin regulates renal water homeostasis via Aquaporins
Gene Ontology:
Molecular function: cAMP binding; cAMP-dependent protein kinase inhibitor activity; cAMP-dependent protein kinase regulator activity; protein binding; protein domain specific binding; protein kinase A catalytic subunit binding; ubiquitin protein ligase binding; protein serine/threonine kinase inhibitor activity
Biological process: negative regulation of activated T cell proliferation; negative regulation of cAMP/PKA signal transduction; negative regulation of gene expression; activation of protein kinase A activity; adenylate cyclase-activating G protein-coupled receptor signaling pathway; cellular response to glucagon stimulus; chemical synaptic transmission; intracellular signal transduction; negative regulation of inflammatory response to antigenic stimulus; negative regulation of smoothened signaling pathway; regulation of transcription by RNA polymerase II; renal water homeostasis; vascular endothelial cell response to laminar fluid shear stress
Cellular component: axoneme; cytoplasm; immunological synapse; membrane; nucleotide-activated protein kinase complex; plasma membrane; plasma membrane raft; protein-containing complex; cAMP-dependent protein kinase complex; ciliary base; cytosol; centrosome; glutamatergic synapse; multivesicular body; neuromuscular junction; sperm head-tail coupling apparatus; synapse
Genetic constraint (gnomAD): Loss-of-function variants: 3 observed, 49.04 expected, observed/expected ratio (o/e) 0.0612, 90% interval 0.027 to 0.16. The upper end of that interval is the gene's LOEUF score, 0.16, which puts it in group 1 of 6, group 1 being the genes least tolerant of losing a copy. Missense variants: 229 observed, 477.55 expected, observed/expected ratio (o/e) 0.48, 90% interval 0.43 to 0.54. Synonymous variants: 179 observed, 170.5 expected, observed/expected ratio (o/e) 1.05, 90% interval 0.93 to 1.19.
Gene-disease validity (ClinGen):
ClinGen rates the evidence that PRKAR1A causes each of these diseases.
Carney complex, type 1 (autosomal dominant): Definitive.
Cancer hallmarks: escaping programmed cell death (suppresses); proliferative signalling (promotes); escaping programmed cell death (promotes); invasion and metastasis (suppresses)
Homologues: Orthologues: chimpanzee PRKAR1A (100% identical), macaque PRKAR1A (99% identical), rabbit PRKAR1A (99% identical), guinea pig PRKAR1A (98% identical), pig PRKAR1A (98% identical), rat Prkar1a (97% identical), mouse Prkar1a (97% identical), tropical clawed frog prkar1a (92% identical), zebrafish prkar1ab (92% identical), zebrafish prkar1aa (91% identical), dog PRKAR1A (87% identical). Paralogues in human: PRKAR1B (81% identical), PRKAR2B (39% identical), PRKAR2A (38% identical), CNBD1 (17% identical).
Diseases named in the same sentence as PRKAR1A in open-access papers:
PRKAR1A is named in the same sentence as 164 diseases in open-access papers, as found by Europe PMC text mining. Sharing a sentence is not in itself a finding about the gene and the disease. The quoted sentences say what the papers report.
Carney complex (48 papers, 2008 to 2026). Carney complex (CNC) is characterized by spotty skin pigmentation, endocrine overactivity and myxomas. "In contrast, our case presents a confirmed clinical and molecular diagnosis of Carney Complex, with two distinct hits in PRKAR1A: a germline pathogenic variant and loss of heterozygosity in the cardiac tumor, consistent with the classic tumor suppressor model." (PMID 40641912, 2025). "Psammomatous MMNSTs have more often been reported in association with Carney complex, and PRKAR1A alterations are common in melanotic schwannoma." (PMID 41030562, 2025). "PBMAH is associated with ARMC5 mutations, whereas PPNAD is linked to Carney complex and involves PRKAR1A mutations." (PMID 41000299, 2025). "Most of them are sporadic, but about 10 % are associated with the Carney complex, an autosomal dominant disorder caused by mutations in protein kinase A regulatory subunit 1 alpha (PRKAR1A)." (PMID 40311368, 2025). "MMNSTs often harbor PRKAR1A mutations, particularly in patients with Carney complex, an autosomal dominant syndrome associated with cardiac myxomas, pigmented skin lesions, and endocrine tumors." (PMID 41030562, 2025). "Phenomena whereby similar germline variants produce different phenotypes have also been identified in other pituitary tumorigenesis genes, notably in PRKAR1A variants promoting Carney complex and acrodysosotosis." (PMID 40064730, 2025). "Carney complex is a rare autosomal dominant genetic syndrome caused mainly by mutations in the PRKAR1A gene, which encodes the regulatory subunit α of the cAMP-dependent protein kinase A (PKA)." (PMID 39050568, 2024). "Developing targeted therapies against PRKAR1A mutations will aid in the treatment of Carney complex, and this will be the focus of our future research." (PMID 39050568, 2024). "Carney complex is an inheritable and autosomal dominant condition, and germline mutations in the gene coding the protein kinase A regulatory subunit 1 alpha (PRKAR1A) located on the locus 17q22-24 were responsible for several phenotypes of this disease." (PMID 38792877, 2024). "We revealed a novel PRKAR1A gene mutation in Chinese patient with Carney complex and review the literature to enhance understanding of Carney complex." (PMID 39050568, 2024). "Carney syndrome (CNC) is a rare autosomal genetic disorder with mutations in the PRKAR1A gene implicated in its pathogenesis." (PMID 38886700, 2024). "Carney complex is a rare autosomal dominant syndrome that has been shown to be associated with inactivation due to PRKAR1A mutations." (PMID 39050568, 2024). "Carney complex is another autosomal-dominant tumor syndrome caused by mutations in PRKAR1A, which acts as a tumor suppressor; 2.5% of individuals with Carney complex develop thyroid cancer." (PMID 37446316, 2023). "Inactivation of PRKAR1A can cause Carney complex type 1 (CNC1, OMIM:160980), an autosomal dominant syndrome characterized by multiple endocrine tumors, including CM." (PMID 37452081, 2023). "Mice with a range of Prkar1a mutations show abnormalities consistent with those seen in humans with Carney Complex." (PMID 36313756, 2022). "A significant proportion of patients with Carney Complex with PRKAR1A mutations also have germline loss-of-function mutations in PDE11A." (PMID 36313756, 2022). "This phenotypic effect of loss-of-function PDE11A mutations is observed in patients with Carney Complex and PRKAR1A mutations who develop Sertoli cell tumors, as described in more detail below." (PMID 36313756, 2022). "Germline mutations in the gene encoding PRKAR1A, a tumor suppressor gene, is associated with Carney Complex phenotype and mutated in 65% of the Carney Complex patients." (PMID 34943205, 2021). "PRKAR1A haploinsufficiency is the primary cause of Carney complex (CNC), a hereditary syndrome characterized by pigmented lesions and benign tumors." (PMID 34087234, 2021).
Carney complex (continued). "The PRKAR1A-mutated subtype occurs in patients with Carney Complex, whereas both PRKCA and PRKA1A altered subtypes can be seen sporadically." (PMID 34943205, 2021). "A somewhat surprising finding was that the protein PRKAR1A, known to be mutated and inactivated in patients with the inherited disease Carney Complex, was increased two-fold in MEN1-KO-BON1 cells relative to BON1 cells." (PMID 32884006, 2020). "PRKAR1A mutations in humans are known to cause Carney complex, an autosomal dominant genetic disease often associated with premature death." (PMID 32212257, 2020). "Mutations in PRKAR1α cause Carney complex, while disturbances of the WRN gene signaling pathway are associated with development of Werner syndrome." (PMID 31247975, 2019). "Genes in this region associated with human phenotypes include PRKAR1A (Carney complex) and KCNJ2 (Andersen/Andersen-Tawil syndrome)." (PMID 24892279, 2014). "Carney Complex is an autosomal dominant disorder that results from inactivating mutations in the protein kinase A regulatory subunity (PRKAR1A) gene, that encodes the type 1α regulatory subunit of cAMP dependent PKA." (PMID 24832650, 2012). "A novel subtype of PRKAR1A mutation was discovered, which may affect the characteristics of the PRKAR1A protein and contribute to the development of Carney complex." (PMID 39050568, 2024). "Carney syndrome is an uncommon autosomal disorder closely linked to mutations in the PRKAR1A gene." (PMID 38886700, 2024). "Identifies mutations in the PRKAR1A gene associated with Carney complex." (PMID 38074042, 2023). "In patients with PPNAD and Carney syndrome, 65–82% had germline PRKAR1A mutations." (PMID 35992106, 2022). "Patients with PRKAR1A mutations are often diagnosed with Carney complex (CNC) in early adulthood, and may die later in life from cardiac complications such as heart failure." (PMID 32212257, 2020). "Carney complex is most commonly due to a mutation of the PRKAR1A gene on chromosome 17q22–24; however, some cases are linked with an unknown gene at 2p16." (PMID 31247975, 2019). "Interestingly, patients of Carney complex, which is an autosomal dominant disease caused by inactivation of the PRKAR1A gene, have a high prevalence of pancreatic tumors, including intraductal papillary mucinous neoplasms (IPMN)." (PMID 28426742, 2017). "This gene may function as a tumor-suppressor gene encoding the regulatory subunit type 1-alpha (R1) of protein kinase A. Recently, mutations in the PRKAR1A gene were estimated to occur in more than 60% of Carney complex patients." (PMID 25890363, 2015). "Carney complex is most commonly due to mutations in the PRKAR1A gene on chromosome 17q22-q24." (PMID 25890363, 2015). "Carney complex is most commonly caused by mutations in the PRKAR1A gene on chromosome 17q22-24." (PMID 25890363, 2015). "Of the total number of cases of Carney complex, 65% are linked to PRKAR1A gene mutation." (PMID 24886234, 2014). "Half of the known Carney complex myxomas can be attributed to mutations in PRKAR1A genes." (PMID 23618320, 2013). "However, PRKAR1A gene mutation testing is helpful for the diagnosis of Carney complex." (PMID 39050568, 2024). "Furthermore, the development of Carney complex is closely related to mutations in the PRKAR1A gene." (PMID 39050568, 2024). "Carney complex (CNC) is a rare multiple neoplasia syndrome inherited in an autosomal-dominant manner caused by loss-of-function mutations of the PRKAR1A gene located at 17q22-24, which encodes the regulatory subunit type I alpha of protein kinase A (PKA)." (PMID 35929903, 2022). "Genetically, the majority are characterized by germline or somatic inactivation of PRKAR1A, a tumor suppressor located on 17q22-24, and a subset are associated with Carney complex (CNC)." (PMID 33921435, 2021).
Carney complex (continued). "The tumor suppressor gene, PRKAR1A, coding for the Type 1alpha regulatory subunit of protein kinase A, a critical cellular component of a number of cyclic nucleotide-dependent signaling pathways, is mutated in Carney complex, a familial neoplasia syndrome that is associated with thyroid tumors." (PMID 18570662, 2008). "We identified a novel mutation in the protein kinase cAMP-dependent type I regulatory subunit α (PRKAR1A) gene in a Chinese patient presenting with multiple recurrent cardiac myxomas, confirming a diagnosis of Carney complex (CNC)." (PMID 40926898, 2025). "Carney complex (CNC) is a rare, autosomal dominant syndrome, most commonly caused by PRKAR1A gene mutations and characterized by pigmented skin and mucosal changes with multiple endocrine and non-endocrine tumours." (PMID 39217593, 2024). "In humans, inactivating mutations or deletions of the PRKAR1A gene have been associated with Carney complex (CNC), an autosomal dominant genetic disorder characterized by spotty skin pigmentation and tumors in the endocrine glands, heart (cardiac myxoma), skin, breast, and other body parts." (PMID 32212257, 2020). "Personal or family history of Carney complex, an autosomal dominant syndrome, or its associated mutations in the PRKAR1A gene located on chromosome 17q24.2-3 (CNC1) and chromosome 2p16 (CNC2) may predispose patients to CMx." (PMID 40552248, 2025). "Furthermore, a high frequency of PDE11A variants has been identified in patients with Carney complex (CNC), especially in those with PRKAR1A mutations." (PMID 41179677, 2025). "Bilateral myxomas may occur sporadically or in association with Carney complex (CNC), an autosomal dominant syndrome characterized by PRKAR1A mutations, multiple myxomas, endocrine tumors, and cutaneous pigmentation." (PMID 41440527, 2025). "The PRKAR1A gene has been identified in patients with Carney complex." (PMID 39720598, 2024). "Carney complex (CNC) is a rare, autosomal dominant syndrome, most commonly caused by heterozygous inactivating mutations of the PRKAR1A gene (encoding a key component of the cAMP signalling pathway) on chromosome 17 (17q23-q24), which may function as a tumour-suppressor gene." (PMID 39217593, 2024). "In addition to their PRKAR1A mutation, LCCSCT patients with Carney Complex have an increased frequency of germline loss-of-function mutations in PDE11A." (PMID 36313756, 2022). "Diagnosing PPNAD preoperatively can be difficult since other signs of the Carney complex are not always present, not all patients have the otherwise typical PRKAR1A mutation, and variations in the appearance of the adrenal glands on CT." (PMID 31440949, 2019). "Interestingly, somatic mutations that result in a similar loss of function have been described in the human RIα locus (PRKAR1α) in patients with Carney complex, a familial multiple neoplasia syndrome characterized by cardiac and extracardiac myxomas, schwannomas, endocrine and gonadal tumors." (PMID 21533282, 2011).
acrodysostosis (19 papers, 2013 to 2025). Acrodysostosis (ACRDYS) is a rare primary bone dysplasia characterized by severe brachydactyly, peripheral dysostosis with facial dysostosis, nasal hypoplasia, and developmental delay. "Two cases harbored heterozygous GNAS mutation, including a novel splice site variant (c.719-30A>T), compatible with pseudohypoparathyroidism, and one had a heterozygous PRKAR1A mutation, compatible with acrodysostosis." (PMID 41155848, 2025). "Two were diagnosed with pseudohypoparathyroidism due to GNAS mutations and one with acrodysostosis caused by a PRKAR1A variant." (PMID 41155848, 2025). "One patient (P8) was diagnosed with acrodysostosis and carried a heterozygous pathogenic variant in the PRKAR1A gene (c.1004 G>T)." (PMID 41155848, 2025). "In this review, we will use the iPPSD nomenclature; specifically, we will use iPPSD4 to refer to acrodysostosis caused by mutations in PRKAR1A and iPPSD5 for acrodysostosis caused by mutations in PDE4D." (PMID 38983619, 2024). "This is highlighted by the prevalence of Cushing’s Syndrome and acrodysostosis for patients with PRKACA or PRKAR1A variants, respectively." (PMID 38481146, 2024). "Several patients with acrodysostosis have been reported with mild-to-severe intellectual disability or mental retardation as a comorbidity, but the cooccurrence of ID with PRKAR1A variants is relatively low." (PMID 38481146, 2024). "One of the patients presenting with ankylosis also has acrodysostosis and was found to have a likely pathogenic heterozygous PRKAR1A variant (NM_212472.2: c.379_380delinsTT; p.Ala127Phe)." (PMID 37361548, 2023). "Acrodysostosis is an inherited disorder of bone formation and cognition produced by mutations in either PRKAR1A or the cAMP-specific phosphodiesterase PDE4D [see ref., especially the Supplemental text file, for a review]." (PMID 36313756, 2022). "Acrodysostosis PRKAR1A mutations are located in the second cAMP-binding domain of RIα, where they perturb the switch between the active (cAMP-bound) and inactive conformations of PKA." (PMID 36313756, 2022). "In humans, patients with acrodysostosis carrying mutations in PRKAR1A that constitutively activates PKA, present with pigmented skin lesions." (PMID 34815795, 2021). "iPPSD4 and iPPSD5 are subtypes including acrodysostosis (ACRDYS) caused by PRKAR1A and PDE4D alterations, respectively." (PMID 33179219, 2021). "Hormone resistances, usually PTH and/or TSH resistance, have been detected in about 60-70% of acrodysostosis patients with a PRKAR1A mutation and in 10-20% of cases with PDE4D mutations." (PMID 29280743, 2017). "Since then, two distinct genetic and phenotypic subtypes of acrodysostosis have been differentiated: acrodysostosis type 1 resulting from defects in PRKAR1A, and acrodysostosis type 2 caused by mutations in PDE4D." (PMID 28515031, 2017). "IUGR has also been described in other iPPSD, such as acrodysostosis with mutations in PRKAR1A or PDE4D, and in patients with mutations in PDE3A." (PMID 29280743, 2017). "Mutations in the PRKAR1A (MIM 188830) gene have been identified in several cases of acrodysostosis with concomitant resistance to multiple hormones." (PMID 25075981, 2014). "This disease continuum may encompass both forms of acrodysostosis (caused by PRKAR1A and PDE4D variants), Albright hereditary osteodystrophy, and pseudohypoparathyroidism (caused by GNAS variants)." (PMID 40917827, 2025). "In a recent report, only 1/9 acrodysostosis patients with PRKAR1A variants were comorbid with ID." (PMID 38481146, 2024). "The precise mutations in PRKAR1A in acrodysostosis are different from those seen in Carney Complex." (PMID 36313756, 2022). "Similarly, most patients with acrodysostosis and a mutation in PRKAR1A or PDE4D are born SGA5,13,15." (PMID 29959430, 2018). "The bone dysplasia observed in patients with acrodysostosis might display a prenatal onset, mostly when caused by PRKAR1A mutations." (PMID 29959430, 2018).